LIN28B (lin-28 RNA binding posttranscriptional regulator B)
Diseases named in the same sentence as LIN28B in open-access papers (continued):
Sharing a sentence is not in itself a finding about the gene and the disease.
breast carcinoma (continued). "Previous studies showed that LIN28B rs7759938 was associated with neither breast cancer risk in European-American women nor the severity of coronary lesions in a Chinese Han population." (PMID 32571380, 2020). "The expression levels of Lin28A and Lin28B in tumor tissues were higher than those in normal breast tissues, the Lin28A expression in HER2-Enriched breast cancer was slightly higher than other sub-type breast cancers, and the Lin28B expression was significantly higher in basal-like breast cancer." (PMID 31754343, 2019). "In addition, CAF64-si-SFCM inhibited the stemness properties in breast cancer cells (CD44high/CD24low/ALDHhigh), and downregulated BMI-1 and lin-28B compared to controls." (PMID 29416775, 2018). "Next, we further evaluated whether CCL18 promoted migration and invasion of breast cancer cells could be inhibited by N-Ras or Lin28b suppression." (PMID 26244871, 2015). "Thus, high Lin28B and low let-7s in tumors may indicate poor prognosis and lung metastasis in breast cancer patients." (PMID 36005690, 2022). "Moreover, Lin28B-induced breast cancer stem cells are the main sources of low-let-7s exosomes." (PMID 35173168, 2022). "To further investigate whether the integrated N-Ras/ERK/PI3K/NFκB/Lin28b signaling pathway was essential for the repression of miR98 by CCL18, we transfected siRNAs targeting N-Ras or Lin28b mRNA into MCF-7 breast cancer cells, which were then exposed to CCL18 (20 ng/ml) for 48 hr." (PMID 26244871, 2015). "The human breast cancer cell line MDA-MB-231, which is invasive and highly metastatic, expresses high levels of Lin28B." (PMID 35173168, 2022). "In breast cancer cells, LINC00665 has been found to act as a sponge for miR-379-5p, reducing the capacity of miR-379-5p to suppress expression of Lin-28 Homolog B (LIN28B)." (PMID 36429005, 2022). "In breast cancer, LINC00665 overexpression facilitates proliferation, migration and invasion of breast cancer cells by upregulating LIN28B and inducing EMT through ceRNA regulating of miR-379-5p21." (PMID 33436545, 2021). "IKKβ targeting reduces breast cancer mammosphere formation and tumourigenicity, and positively regulates Lin28B and SRY (sex determining region Y)-box 2 (SOX2) to promote breast cancer stemness and reduces breast GD2+ TICs, thereby reducing metastasis." (PMID 32823550, 2020). "After treatment with CCL18, the N-Ras/ERK/PI3K/NFκB/Lin28b pathway was consistently active, which was maintained by down-regulation of miR98 and miR27b, leading to EMT of epithelial breast cancer cells." (PMID 26244871, 2015). "Lin28B reduced the expression of let-7s in breast cancer exosomes and regulated the expression of CXCL, IL-6, and IL-10 in neutrophils, resulting in immunosuppressive PMN, thus promoting lung metastasis of breast cancer." (PMID 37046819, 2023). "have found that Lin28B is involved in neutrophil recruitment and N2 conversion through let-7s-carrying exosomes to alter the immune status in the TME, thereby establishing an immunosuppressive PMN and ultimately inducing lung metastasis of breast cancer." (PMID 37534210, 2023). "Similarly, overexpression of Lin28B in TNCB was found to promote lung and breast cancer metastasis through the development of an immune-suppressive pre-metastatic niche marked by neutrophil recruitment and subsequent conversion of N2 phenotype." (PMID 36230562, 2022). "Decreased NF-κB transactivation was also confirmed by luciferase reporter assay in hypoxic CAIX-knockouts, displaying also decreased levels of LIN28B; this correlates with the determination that CAIX expression is required for the activation of NF-κB in hypoxic breast cancer cells." (PMID 32560271, 2020). "Lin28B is mainly expressed in TNBC and could promote breast cancer progression." (PMID 36430471, 2022).
breast carcinoma (continued). "The expression of LINC00665, miR-379-5p, and LIN28B in breast cancer and normal breast tissues were obtained from the TCGA database and we found upregulation of LINC00665 and LIN28B expression and a downregulation of miR-379-5p expression in breast cancer tissues." (PMID 31907362, 2020). "Thus, we utilized the mRNA expression array data from TCGA to investigate the correlation between MZF1 and lin28A and lin28B mRNA (LIN28A and LIN28B) in breast cancer and found that MZF1 expression correlates positively with the expression of lin28A, but not lin28B." (PMID 29396433, 2018).
ovarian carcinoma (35 papers, 2011 to 2025). A malignant neoplasm originating from the surface ovarian epithelium. "Beyond its role in MB, LIN28B has been implicated in several other malignancies, including hepatocellular carcinoma, colorectal cancer, and ovarian cancer, where it contributes to tumour progression, stemness, and resistance to therapy." (PMID 40265419, 2025). "In the present study, we linked oncogenic protein LIN28B to the apoptosis pathway and identified the molecular mechanism for the antiapoptotic function of LIN28B in ovarian cancer cells." (PMID 30174831, 2018). "This is the first report to experimentally associate LIN28B with the apoptosis pathway in ovarian cancer cells, as well as to discover the suppressive function of LIN28B on BIM expression." (PMID 30174831, 2018). "Lin28B is directly regulated by c-Myc and expression is associated with proliferation and invasiveness of multiple advanced human malignancies, including hepatocellular carcinoma, ovarian cancer, germ cell cancer and colorectal cancer." (PMID 27007052, 2016). "RNF144A inhibits the growth of tumors and the characteristics of ovarian cancer stem cells by controlling the degradation of LIN28B via the ubiquitin-proteasome pathway." (PMID 38313020, 2024). "After initially demonstrating that LIN28B high expression in patients with ovarian cancer significantly reduced overall survival, following experiments revealed that the knockdown of LIN28B significantly increased the number of apoptotic cells." (PMID 37304235, 2023). "Loss of hnRNPA2B1 inhibits malignant capability and promotes apoptosis via down-regulating Lin28B expression in ovarian cancer." (PMID 37639158, 2023). "Consistent to previous findings, knockdown of LIN28B attenuated the viability of ocular melanoma and ovarian cancer cells." (PMID 35780125, 2022). "In ovarian cancer, combined high expression of IGF2BP3 and of Lin28B, another RNA-binding protein, was strongly associated with chemoresistance and poor disease outcome, based on elevated expression of hCTR1, a copper transporter involved in platinum uptake." (PMID 35615150, 2022). "It was reported that hnRNPA2B1 regulates expression of Lin28B via binding to Lin28B mRNA and enhancing its stability, thus promoting malignant capability of ovarian cancer." (PMID 34496888, 2021). "LIN28B inhibits the apoptosis of ovarian cancer cells and promotes cancer progression by binding to AKT2 mRNA and increasing the expression of the protein." (PMID 33193718, 2020). "Our results indicated that NEAT1 promoted ovarian cancer cell proliferation and metastasis partly in a LIN28B-regulated manner." (PMID 30154460, 2018). "The highly restricted expression of LIN28B in adult tissues suggests that LIN28B holds promise as a novel candidate for targeted therapy in developing new strategies for the treatment of ovarian cancer." (PMID 30174831, 2018). "We examined the expression of LIN28B in two large collections of epithelial ovarian cancer specimens using immunohistochemistry." (PMID 30174831, 2018). "The cell-wounding and Transwell assays also showed that NEAT1 knockdown partially attenuated the effects of LIN28B overexpression in ovarian cancer cells." (PMID 30154460, 2018). "Here we report that LIN28B was expressed in over half of the patients with epithelial ovarian cancer who were examined (n = 584)." (PMID 30174831, 2018). "RNA-IP microarray analysis suggested that LIN28B binds to mRNAs that are associated with the DNA damage pathway, such as AKT2, in ovarian cancer cells." (PMID 30174831, 2018). "A rescue functional assay confirmed that the LIN28B/NEAT1 axis contributed to oncogenic functions in ovarian cancer cells." (PMID 30154460, 2018). "In ovarian cancer, the level of Lin28B expression is correlated with tumor stage and lymph node metastasis." (PMID 28947981, 2017). "Adult hepatocellular carcinomas, germ cell tumors and ovarian carcinomas often ectopically activate LIN28 or LIN28B to restore oncofetal programs." (PMID 27879203, 2016).
ovarian carcinoma (continued). "LIN28B is a highly conserved RNA-binding protein that is frequently upregulated in various cancers including ovarian cancer, contributing to cell death resistance, tumor-associated inflammation, genome instability, acquisition of immortality, and evasion of immune destruction." (PMID 37270714, 2024). "hnRNPA2B1 improved the stability of Lin28B mRNA and enhanced malignant potential of ovarian cancer." (PMID 34966670, 2021). "Rescue assays confirmed the function of the LIN28B/NEAT1 axis in ovarian cancer cells." (PMID 30154460, 2018). "LIN28B suppressed apoptosis through downregulating the expression of BIM in ovarian cancer cells." (PMID 30174831, 2018). "Functional experiments demonstrated that LIN28B inhibited ovarian cancer cell apoptosis." (PMID 30174831, 2018). "We had experimentally validated this with an in vitro BrdU labeling analysis and found that LIN28B could promote cell cycle transition after serum starvation in ovarian cancer cells." (PMID 30174831, 2018). "Subsequently, Gene Ontology (GO) analysis of these 1555 mRNAs was performed to explore the signaling pathways that might be controlled by LIN28B in ovarian cancer cells." (PMID 30174831, 2018). "Clinical data from The Cancer Genome Atlas database demonstrated a negative correlation between the LIN28B mRNA expression level and overall survival of 582 ovarian cancer patients, which further supported our hypothesis that LIN28B might act as an oncogene in the disease." (PMID 30174831, 2018). "FISH on a TMA of 239 ovarian tumours, including 73 of known molecular subtype found evidence for rearrangement between HACE1 and LIN28B in only a single core from a HG-SOC tumour of unknown molecular subtype, suggesting this mechanism for LIN28B up-regulation is rare in ovarian carcinoma." (PMID 21533284, 2011). "In ovarian cancer, HNRNPA2B1 ameliorated tumor growth through binding and stabilizing Lin28B mRNA resulting in poor survival." (PMID 32710725, 2020). "LIN28B suppressed BIM expression at the transcriptional level and conferred apoptotic resistance in ovarian cancer cells." (PMID 30174831, 2018). "In particular, we could show that IGF2BP1 shields the transcripts of LIN28B and HMGA2 as well as its own mRNA from let-7-mediated downregulation in ovarian cancer-derived cells, thus promoting an aggressive tumor phenotype." (PMID 32545414, 2020). "In these conditions, IGF2BP1, LIN28B and HMGA2 form a partially self-sustaining oncogenic triangle, where HMGA2 enhances cell growth, and IGF2BP1 and LIN28B promote the migratory and self-renewal potential of ovarian cancer cells." (PMID 31434359, 2019). "To examine whether NEAT1 could bind to other RBPs in ovarian cancer cells, we performed a bioinformatics analysis, RNA pulldown assay, and RIP assay, which revealed that NEAT1 could combine with LIN28B." (PMID 30154460, 2018). "For example, the hPGC gene LIN28B plays a very important role in the inhibition of apoptosis through regulation of the AKT2/FOXO3A/BIM axis in ovarian cancer cells, indicating a novel target based on hPGC pluripotency in the diagnosis and therapeutics of ovarian cancer." (PMID 36184610, 2022). "Furthermore, irrespective of its role in cell invasion, LIN28B displays an antiapoptotic role in ovarian cancer cells through the regulation of the protein kinase Bβ (AKT2)/forkhead box O3a (FOXO3A)/Bcl-2-like 11 (BIM) axis." (PMID 32528950, 2020). "Additionally, LIN28B is reported to promote metastasis in colon and ovarian cancers, and some studies claim that MYCN could be directly responsible for the deregulation of LIN28B." (PMID 33081056, 2020).
hepatocellular carcinoma (30 papers, 2012 to 2025). A malignant tumor that arises from hepatocytes. "Definitive association of let7b and LIN28B require luciferase reporter assays; such studies have performed for human hepatocellular cancer and confirm the role of let7b as a negative regulator of LIN28B." (PMID 24047116, 2013). "LIN28A was originally identified in Caenorhabditis elegans as a heterochronic gene and shown to affect embryonic developmental timing, whereas LIN28B was first identified in hepatocellular carcinoma (HCC)." (PMID 40265419, 2025). "Here, we demonstrate that human hnRNP Q interacts with LIN28B by co-immunoprecipitation in hepatocellular carcinoma cells." (PMID 38976670, 2024). "Together, our findings suggest that hnRNP Q interacts with LIN28B and modulates the LIN28B/let-7 axis in hepatocellular carcinoma." (PMID 38976670, 2024). "In fact, enhanced aerobic glycolysis has been observed in hepatocellular carcinomas overexpressing LIN28B, where LIN28B acts by targeting the metabolic enzyme PDH kinase 1 (PDK1)." (PMID 38338881, 2024). "TRIM71 has been implicated in the growth and tumorigenicity of hepatocellular carcincoma, and LIN28B has been demonstrated to promote hepatocellular carcinoma cell progression as well." (PMID 38976670, 2024). "Nuclear factor-kappaB (NF-κB) is suggested to be involved in mediating paclitaxel resistance in hepatocellular carcinoma (HCC) via upregulating Lin28B." (PMID 33187385, 2020). "In particular, in mice the overexpression of Lin28b, the main liver isoform, is able to initiate hepatocellular carcinoma." (PMID 32709089, 2020). "LIN28B over-expression mediates the suppression of let-7 expression by HBV X protein (HBx) in HepG2 hepatoma cells." (PMID 32571380, 2020). "To date, Lin28 and Lin28B have been reported to be distinctively or exclusively expressed in several tumors, including hepatocellular carcinoma, esophageal cancer, oral squamous cell carcinoma, and colorectal cancer." (PMID 28947981, 2017). "Our finding is consistent with our report that HBx was able to activate Sp1 in up-regulation of Lin28A/Lin28B in hepatoma cells." (PMID 27050367, 2016). "Lin28A was first discovered in nematode Caenorhabditis elegans, and was proved to regulate the developmental timing, whereas Lin28B was first discovered in hepatocellular carcinoma(HCC), where it is highly expressed." (PMID 27793004, 2016). "Many studies have shown that LIN28A/LIN28B promotes and let-7 inhibits invasion and metastasis in various cancer types, including colon cancer, breast cancer, hepatocellular carcinoma, pancreatic cancer, gastric cancer, lung cancer and esophageal cancer." (PMID 26123544, 2015). "As a homologue of Lin28, LIN28B has primarily been cloned from hepatocellular carcinomas, and its overexpression has been shown to promote cancer cell proliferation." (PMID 25360631, 2014). "LIN28B is frequently overexpressed in multiple cancers, especially advanced types such as progressive hepatocellular carcinoma, epithelial ovarian cancer, Wilm's tumour and germ cell tumours." (PMID 25360631, 2014). "Lin28B is highly expressed in the majority of human hepatocellular carcinomas and embryonic stem cells, and regulate cell pluripotency as well as cancer growth." (PMID 23667675, 2013). "Lin28B protein, a homologue of Lin28, is also overexpressed in hepatocellular carcinoma and induction of expression with exogenous Lin28B promoted cancer cell proliferation." (PMID 22433967, 2012). "In addition, Lin28 is also overexpressed in hepatocellular carcinoma, and regulating Lin28B enhance the anti-tumor activity of GPC3 CAR-T cells, enabling GPC3 CAR-T cells to better treat hepatocellular carcinoma." (PMID 39136031, 2024). "Therefore, we aimed to illuminate the function of the lin28B/Let-7c/MYC axis in hepatocellular carcinoma." (PMID 36057607, 2022).
hepatocellular carcinoma (continued). "Additionally, overexpression of Lin28B in transgenic murine models was sufficient to induce hepatoblastoma and hepatocellular carcinoma, while deletion or silencing of Lin28B gene prolonged survival." (PMID 36230562, 2022). "However, Lin28B, which was first identified in hepatocellular carcinoma, has important functions during the transformation of cells from an inflammatory to malignant state." (PMID 28947981, 2017). "Lin28B is localized in the cytoplasm of Huh7 hepatoma cells." (PMID 28947981, 2017). "We previously reported that HBx activated Lin28A/Lin28B through Sp1/c-Myc in hepatoma cells." (PMID 27050367, 2016). "Interestingly, we have reported that HBx activates Lin28A/Lin28B through Sp1/c-Myc in hepatoma cells." (PMID 27050367, 2016). "LIN28B was first identified in hepatocellular carcinoma, where levels of the protein were high." (PMID 26123544, 2015). "Similarly, transgenic mice overexpressing LIN28B in the liver develop hepatic cancer with higher glucose consumption compared to the surrounding normal tissue, mirroring the behavior of a subset of aggressive human hepatocellular carcinomas." (PMID 38338881, 2024). "We aimed to evaluate the critical involvement of lin28B and Let-7c in the carcinogenesis of human hepatocellular carcinoma (B-HCC)." (PMID 36057607, 2022). "The RNA-binding protein Lin-28 homolog B (LIN28B), first characterized in hepatocellular carcinoma, functions as an oncogenic driver through selective inhibition of let-7 tumor-suppressive microRNA maturation." (PMID 40740861, 2025). "In hepatocellular carcinomas, the relationship between SOX6 and LIN28B expression is less clear indicating more intricate regulatory dynamics." (PMID 38704454, 2024). "This study investigated the association of LIN28B rs314277, rs314280, rs369065 and rs7759938 polymorphisms in patients with chronic HBV infection, a major cause of liver disease including hepatocellular carcinoma (HCC)." (PMID 32571380, 2020). "Multiple miR-125b targets were found to be upregulated in hepatocellular carcinoma, including BCL2, BCL2 like 2 (Bcl-W), myeloid cell leukemia sequence 1 (Mcl-1), interleukin-6 receptor (IL6R), lin-28 homolog B (LIN28B) and placenta growth factor (PIGF)." (PMID 24774301, 2014). "Although the correlation between Let-7c and Lin28B expression was not analyzed in more other hepatocellular carcinoma cells in this study, there have been relevant literatures to clarify their regulatory mechanism." (PMID 36057607, 2022). "Overexpression of Lin28A and Lin28B is associated with poor prognosis in various cancers, such as oral squamous cell carcinoma (OSCC), colon cancer, epithelial ovarian carcinoma (EOC), gastric cancer, hepatocellular carcinoma (HCC), breast cancer, esophagus cancer, and other malignancies." (PMID 30976203, 2019). "In terms of hepatitis B virus (HBV), a major cause of liver disease including hepatocellular carcinoma (HCC) worldwide, LIN28B is involved in the regulation of HBV replication and plays an oncogenic role in HCC." (PMID 32571380, 2020).